GFAP (glial fibrillary acidic protein)
Diseases named in the same sentence as GFAP in open-access papers (continued):
Sharing a sentence is not in itself a finding about the gene and the disease.
meningitis (continued). "Regarding the biological relevance as well as the pathophysiological aspects of GFAP in meningitis, a probable astrogliosis followed by bacterially triggered inflammation of the CNS could be the morphological correlate of the observed GFAP release into the CSF." (PMID 20386697, 2010). "A heat map was created to visualize the concentrations of DEFA1, GFAP, ALOX5, and S100B in the meningitis and healthy control groups." (PMID 38115295, 2023). "In this cohort, the serum concentration of GFAP was elevated in WNV encephalitis and meningitis patient groups, highlighting potential neuronal inflammation and vascular damage, and correlating with a previous WNV infection description." (PMID 35458486, 2022). "We also observed a significant increase in the expression of GFAP-positive cells in the PFC (P < 0.01) and hippocampus (P < 0.01) of the meningitis group, 24 h after infection, as compared to the levels in the control group." (PMID 31901235, 2020). "DEFA1, GFAP, ALOX5, and S100B successfully distinguished patients with meningitis from controls." (PMID 38115295, 2023). "Similarly, the expression of GFAP was also elevated in both the PFC (P < 0.01) and hippocampus (P < 0.05) of the 10-day meningitis group compared to the levels of the controls." (PMID 31901235, 2020). "The meningitis-induced increase in GFAP+ cell densities was ameliorated in Fpr1−/− but not Fpr2−/− mice (p < 0.01; two-way ANOVA followed by Bonferroni test)." (PMID 33121515, 2020). "In human meningitis, we found that epithelial cells and glial cells of the subependyma failed to express MHC class II antigens but in contrast, were strongly stained for GFAP, a classical marker of ependymal cell activation." (PMID 16948860, 2006). "In future prospective studies, screening GFAP-Abs in patients with inflammatory PNS disease of unknown etiology, associated or not with CNS symptoms or meningitis, may be useful to better define the spectrum of GFAP-Abs-related disease phenotypes." (PMID 37540278, 2023). "Subsequent RT-PCR analyses confirmed our assay results: CL-treated meningitis animals showed higher expression levels of CCL2 and CXCL2 (but not GFAP) compared to PBSL-treated mice." (PMID 40988032, 2025). "The increased levels of vimentin in the LOH infants must be a direct consequence of infection affecting the brain but the lack of GFAP in LOH indicates that the source is unlikely to be astroglial and may be microglial, endothelial or leptomeningeal since many patients present with meningitis." (PMID 24351234, 2013).
dementia with Lewy bodies (20 papers, 2018 to 2025). "Of note, a rise in plasma GFAP levels is also seen in Lewy body dementia and FTD, suggesting that plasma GFAP levels are reflective of the reactive astrogliosis occurring in neurodegeneration more broadly." (PMID 38279230, 2024). "Compared to healthy controls, GFAP levels have been found to be higher in the CSF of AD, dementia with Lewy bodies (DLB), frontotemporal lobar degeneration (FTLD) and Creutzdfeldt-Jakob disease (CJD) patients, whereas S100β was found to be elevated in CJD, but not in AD." (PMID 29922147, 2018). "Higher CSF levels of GFAP were previously reported in FTLD as compared to AD and dementia with Lewy bodies, and increased serum GFAP correlated with the rate of temporal atrophy in GRN carriers." (PMID 34638637, 2021). "Further validation of this blood-based biomarker is needed to further examine the utility of plasma GFAP for identifying a positive amyloid PET status, among others in a cohort in which non-AD dementia patients with amyloid co-pathology (e.g., Lewy body dementia) are included." (PMID 32988409, 2020).
meningioma (20 papers, 2012 to 2025). A generally slow growing tumor attached to the dura mater. "The expression of GFAP by meningothelial cells in meningioma is rare, suggesting a possible distinct precursor cell type associated with this microcystic meningioma variant, different from the precursor cells typically seen in classic meningiomas." (PMID 39139315, 2024). "Surprisingly, and in contrast to other studies, more cells positive for GFAP or BIIIT were detected in grade II/III meningiomas." (PMID 29849507, 2018). "For highly significant grade-related differential markers, single positive staining of FZD9+ or GFAP+ was statistically significantly higher in grade II/III meningiomas (Brown–Forsythe ANOVA, P < 0.01)." (PMID 29849507, 2018). "There are a number of examples of GFAP-positive meningioma reported in literature but these all are intracranial and extra-axial." (PMID 26155457, 2015). "Considering the combination of extensive hyalinization with cytokeratin positivity the tumor was thought to be most consistent with a hyalinized meningioma with GFAP positivity." (PMID 26155457, 2015). "GFAP-positive meningiomas are rare, and these include the recently described ‘whorling-sclerosing’ variant." (PMID 26155457, 2015). "All patients with meningiomas had GFAP < 226 pg/mL and FABP4 > 7,736 pg/mL." (PMID 38879494, 2024). "All markers could be detected in all tumors, however, Frizzled 9 and GFAP had differential expression in grade II/III compared with grade I meningioma tissues." (PMID 29849507, 2018). "The cells in both benign and malignant parts were positive for vimentin and epithelial membrane antigen (EMA), partially positive for S-100, but negative for cytokeratin, Schwann/2E, glial fibrillary acidic protein (GFAP) and Olig2, suggesting that the tumor cells originated from a meningioma." (PMID 27245327, 2016). "We present the first reported case of an intraspinal, GFAP-positive meningioma." (PMID 26155457, 2015). "Normally, meningioma cells do not express GFAP, except in cases involving brain invasion, where a distinct meshwork of cells is formed, consisting of meningothelial cells from the tumor interwoven with brain astrocytes expressing GFAP." (PMID 39139315, 2024). "Regions that were significantly frequently occurring in grade II/III but never in grade I meningiomas included those that were positive for CD133+SOX2±Vimentin+FZD9+GFAP+BTIII+SSEA4+Olig2+, and Nestin+Ki67+CD133+Vimentin+FZD9+GFAP+BTIII+SSEA4+Olig2+." (PMID 29849507, 2018). "Sub regions that showed multiple co-staining of markers including CD133, Frizzled 9, GFAP, Vimentin, and SSEA4, but not necessarily the proliferation marker Ki67, were highly associated with grade II/III meningiomas." (PMID 29849507, 2018). "The main difference here is that astroblastoma is immunoreactive with GFAP whereas the meningioma is not; choroid plexus papilloma is focally GFAP positive." (PMID 27568373, 2016). "An important atypical finding was the expression of glial fibrillary acidic protein (GFAP), which is primarily expressed in astrocytes rather than meningioma cells." (PMID 39139315, 2024). "Glial fibrillary acidic protein, CD99, CD34, S-100 protein, neuron specific enolase, neurofilament, cytokeratin, cytokeratin 19, and Bcl-2 were negative in MA and meningioma area." (PMID 23198201, 2012). "Meningioma cells of all subtypes of tumors were positive for human epithelial membrane antigen (EMA) and vimentin staining and desmoplakin staining, and negative for markers of neural cell types such as GFAP for astrocytes and β-tubulin III for neurons (data not showed)." (PMID 22754374, 2012).
Hypertension (19 papers, 2012 to 2025). The presence of chronic increased pressure in the systemic arterial system. "The Spearman/Pearson analysis revealed a positive correlation between the serum levels of UCH-L1 and GFAP in individuals with hypertension." (PMID 40649119, 2025). "Both clinical and animal studies have found that disorders of glucolipid metabolism and hypertension can induce reactive activation of brain astrocytes and overexpression of glial fibrillary acidic protein (GFAP)." (PMID 38800473, 2024). "Hypertension (in a rat model) influences expression of GFAP in the NTS, suggesting an astrocytic component to the physiological response." (PMID 32535136, 2020). "In males, AngII induced hypertension, and this resulted in an increase in the density of the astrocyte marker glial fibrillary acidic protein (GFAP) in the subgranular hilus and a decrease in the density of the microglial marker ionized calcium binding adapter molecule (Iba-1) in the CA1 region." (PMID 36206386, 2022). "To better understand the consequences of elevated blood pressure on the young adult brain, we conducted an exploratory investigation of the impact of hypertension on the expression of microglia and astrocyte markers—Iba-1 and GFAP, respectively—in the hippocampus and mPFC of male mice." (PMID 36206386, 2022). "Differences in gonadal hormones or the sensitivity to AngII hypertension may account for divergences in GFAP and Iba-1 in males and females." (PMID 36206386, 2022). "Furthermore, SHR rats showed significant loss of caveolin-1 protein levels and induction of iNOS and GFAP levels compared with WKY rats, which suggests that hypertension aggravates inflammatory damage after cerebral ischemic injury." (PMID 24961257, 2012). "Finally, in a 2-kidney 1-clip rat model where blood supply to one kidney is partially blocked to activate the renin-angiotensin-aldosterone system and produce hypertension, a greater number GFAP immunoreactive cells are observed in the NTS when compared with normotensive controls." (PMID 32535136, 2020). "Hypoxia, hypertension, or HFS diets increase GFAP content and remodel astrocyte morphology." (PMID 41227339, 2025). "To determine whether hypertension evoked structural changes to IC astrocytes from WKY and SHR, we measured the percent area of GFAP, a specific astrocyte cytoskeletal protein marker, in the region." (PMID 28270592, 2017).
experimental autoimmune encephalomyelitis (18 papers, 2008 to 2025). An autoimmune demyelinating disease of the central nervous system that is produced experimentally in animals by the injection of homogenized brain or spinal cord in Freund's adjuvant. "An increase in mRNA encoding CXCL10 in experimental autoimmune encephalomyelitis (EAE)-affected mouse brains under an inflammatory state was related to an increase in GFAP expression and astrogliosis." (PMID 35892669, 2022). "In experimental autoimmune encephalomyelitis (EAE), loss of claudin-5 is a primary event in affecting the BBB disruption due to the overexpression of VEGF-A from glial GFAP positive astrocytes." (PMID 35456999, 2022). "In this study, we focused on the progeny of NG2-glia derived from individual embryonic glial fibrillary acidic protein-expressing ￼￼ progenitors (GFAP+) in the brain of mice in which experimental autoimmune encephalomyelitis (EAE) was induced." (PMID 32455842, 2020). "Experimental autoimmune encephalomyelitis was induced in transgenic mice expressing an injury responsive luciferase reporter in astrocytes (GFAP-luc)." (PMID 18237444, 2008). "Induction of experimental autoimmune encephalomyelitis (EAE) in transgenic mice expressing a dominant-negative interferon-γ receptor under the human glial fibrillary acidic protein promoter (GFAPγR1Δ) causes severe non-remitting disease associated with sustained TNF." (PMID 29690885, 2018). "Using this methodology, we report the identification of GFAP+ exosomes in blood and then use a mouse model of inflammatory demyelination, experimental autoimmune encephalomyelitis (EAE), to examine whether the abundance of GFAP+ exosomes in blood circulation changes during clinical illness." (PMID 28663721, 2017). "In mouse models, FABP7 expression was up-regulated in glial fibrillary acidic protein (GFAP)-positive cells in response to spinal cord injury and autoimmune conditions, including experimental autoimmune encephalomyelitis." (PMID 38069360, 2023). "In the progression of experimental autoimmune encephalomyelitis (EAE), both fibrous and protoplasmic astrocytes were broadly and reversibly activated in the brain and spinal cord, indicated by marked upregulation of glial fibrillary acidic protein (GFAP) and other astrocytic proteins." (PMID 24252623, 2013). "Recently, however, bioluminescent imaging of GFAP activity using transgenic GFAP-luc mice has been reported to measure astrogliosis in animal models of kainic lesions, prion infection, ischemic injury, and experimental autoimmune encephalomyelitis (EAE), but has not been described in a tumor model." (PMID 21247490, 2011). "In the rodent model of MS, experimental autoimmune encephalomyelitis (EAE), conditional null mouse mutants lacking S1P1 on GFAP-expressing astrocytes but not on neurons showed attenuation of both EAE disease and FTY720-P efficacy." (PMID 28913617, 2017).
memory impairment (18 papers, 2011 to 2026). "In the present study, pinocembrin was demonstrated to decrease memory impairment, neurological scores, neuronal loss in the hippocampus and the number of GFAP-positive cells in the hippocampal CA1 region of TGCI rats." (PMID 25187841, 2014). "A recent study showed that the number of GFAP-positive astrocytes is closely correlated with memory impairment and neuronal loss, meaning that the inflammatory response of astroglial cells is a key event in memory disruption and neuronal cell death." (PMID 23071606, 2012). "Therefore, based on these findings and the results of the present study, elevated levels of GFAP can be considered a possible mechanism for memory impairment caused by STZ." (PMID 37970441, 2023). "Recently published serum GFAP elevations in chronic heart failure patients and independent relations to memory impairment further support the concept that the increased risk for AD after MI might be triggered by chronic glial activation or damage." (PMID 36142218, 2022). "Considering all findings, TCE treatment mitigated scopolamine-induced memory impairment by reducing proinflammatory cytokines and GFAP expression while concurrently increasing 5-HT concentration and neuronal density in the hippocampus." (PMID 40458441, 2025). "Glial fibrillary acidic protein (GFAP), an astrocyte marker, is associated with memory impairment and neuronal reduction." (PMID 35721176, 2022). "In the brain, neuroinflammation is manifested by elevated levels of GFAP, a marker of astrogliosis, or Iba1, a marker of microgliosis; neuroinflammation could contribute to memory impairments, and further negatively influence adult neurogenesis." (PMID 36126192, 2022). "The level of GFAP-positive astrocytes and CD45-positive microglia might indicate the severity of local inflammation response, which is correlated with memory impairment and neuronal loss." (PMID 27689994, 2016). "This study demonstrated that bilateral administration of STZ (icv) resulted in memory impairment, as indicated by changes in behavior in the ORT and inhibitory avoidance, as well as increased oxidative stress and activation of AChE and GFAP." (PMID 38391705, 2024).
ocular hypertension (18 papers, 2012 to 2026). Abnormally high intraocular pressure. "This ocular hypertension was associated with an activation of macroglial cells as shown by a strong GFAP staining on the retinal sections of laser-treated eyes." (PMID 35275950, 2022). "After adjusting to normotensive fellow eyes, the axon counts indicated approximately 45% loss with 12 week of ocular hypertension in IκKβf/f controls, but 18% loss in GFAP-IκKβ mice." (PMID 32859212, 2020). "Multiplex immunoassays detected decreased titers of multiple proinflammatory cytokines in the ocular hypertensive GFAP/cFLIP and GFAP/cFLIPL retina and optic nerve compared to ocular hypertensive controls." (PMID 38824526, 2024). "An exciting outcome of the NanoString-based gene profiling in ocular hypertensive samples included NF-κB components, as RelA (p65) decreased (p = 0.002) and RelB (p = 0.02) showed increased RNA counts in GFAP/cFLIP mice compared to controls." (PMID 38824526, 2024). "Interestingly, the ganglion and astrocyte densities observed in myopic marmosets are similar to those observed in marmosets induced with ocular hypertension, which may represent early markers of ganglion cell dysfunction/loss and GFAP reactivity observed in glaucomatous marmosets." (PMID 39769248, 2024). "Compared to ocular hypertensive cFLIPf/f or cFLIPLf/f, ocular hypertensive GFAP/cFLIP or GFAP/cFLIPL presented faint alterations in these quantitative parameters." (PMID 38824526, 2024). "When the GFAP immunolabeling pattern of astroglia was studied in whole-mounted retinas, reactive astroglia in ocular hypertensive samples exhibited increased intensity and percentage coverage of GFAP labeling as expected." (PMID 38824526, 2024). "Luminex-based analysis showed decreased titers of multiple cytokines and chemokines in ocular hypertensive GFAP/cFLIP and GFAP/cFLIPL mice compared to ocular hypertensive controls at 12 weeks of ocular hypertension." (PMID 38824526, 2024). "GFAP staining of retinal flat mounts also established marked reactive astrogliosis after 8 weeks of mild ocular hypertension." (PMID 38610040, 2024). "Compared to ocular hypertensive cFLIPf/f controls, the retinal astroglia isolated from ocular hypertensive GFAP/cFLIP presented a significant increase or decrease in 46 out of 248 genes studied." (PMID 38824526, 2024). "On the contrary, RelB expression and phospho-RelB were increased, supporting an upregulated transcriptional function of RelB in ocular hypertensive GFAP/cFLIP compared to ocular hypertensive controls." (PMID 38824526, 2024). "There is also evidence for increased GFAP protein expression in rats and mice as early as 1 day following acute ocular hypertension." (PMID 38983517, 2022). "Immunohistochemical staining of GFAP revealed similar activation of astrocytes in the retinal GCL after induction of ocular hypertension or systemic hypotension." (PMID 35396550, 2022). "GFAP protein expression is certainly increased in chronic models of ocular hypertension and in glaucomatous eyes." (PMID 38983517, 2022). "In an ocular hypertension (OHT) primate model, GFAP immunoreactivity appeared in the LGN, and the loss of metabolic activity was accompanied by enhancement of GFAP immunoreactivity." (PMID 33889083, 2021). "We detected more than three-fold lower enzyme-linked immunosorbent assay (ELISA) titers of pro-inflammatory cytokines in ocular hypertensive GFAP-IκKβ retinas and optic nerves compared to ocular hypertensive IκKβf/f controls." (PMID 32859212, 2020). "The morphological response of microglia to ocular hypertension (a shift from ramified morphology to reactive morphology) was less prominent in ocular hypertensive GFAP-IκKβ retinas than ocular hypertensive IκKβf/f controls." (PMID 32859212, 2020). "The RGC counts in ocular hypertensive eyes (when adjusted to normotensive fellow eyes) were approximately 40% at 12 weeks of ocular hypertension in controls, but 15% in GFAP-IκKβ mice." (PMID 32859212, 2020).